EZH2 (enhancer of zeste 2 polycomb repressive complex 2 subunit)
Diseases named in the same sentence as EZH2 in open-access papers (continued):
Sharing a sentence is not in itself a finding about the gene and the disease.
tumor (continued). "Similar to EZH2, EHMT2 inhibits the transcription of tumor suppressors by promoting the levels of H3K9me1/H3K9me2." (PMID 34409024, 2021). "Collectively, all these studies underscore the tumor-promoting effects of N-methyltransferases such as NNMT and EZH2 in TAFs." (PMID 34359678, 2021). "The high EZH2, SUZ12, and EED expression in tumor samples has been attributed to the decreased patient survival in several tumor types." (PMID 34202528, 2021). "The difference in expression comparing tumor and normal tissues were found to be significant in eight genes (PLAU, EGR1, IL6, EGFR, EZH2, BMP4, CCNB1, NMI)." (PMID 34077304, 2021). "The genetic knockout of EZH2 prolonged survival when H3K27M mouse tumour cells were orthotopically transplanted, demonstrating that EZH2 activity is required for tumour growth in vivo." (PMID 34944870, 2021). "Our studies provide the first proof-of-concept that effective targeting of EZH2 can reverse HBEC transformation and impede tumor development." (PMID 33632299, 2021). "Our previous study also showed that EZH2 expression is also higher in GBC tissues and overexpression of EZH2 enhanced GBC tumor progression." (PMID 34789260, 2021). "EZH2, the core enzymatic subunits of PRC2, plays a pivotal role in tumor carcinogenesis and progression via modulating many pro-oncogenic and pro-survival signaling pathways." (PMID 33456353, 2021). "Treatment with the EZH2 inhibitor,EPZ011989, in muscle-invasive bladder cancer bearing nude mice increased NK cell infiltration and activation in the tumor specimens." (PMID 33403469, 2021). "EZH2, a catalytic subunit of PRC2, is an oncogenic protein that silences the expression of various tumor-inhibitor miRNAs, such as miR-125b, miR-139-5p, miR-101, let-7c, and miR200b, and is typically increased in human cancers." (PMID 34381816, 2021). "CDF has been shown to inhibit tumour progression by modulating multiple molecular targets including Phosphatase and tensin homolog (PTEN), Enhancer of zeste homolog 2 (EZH2), and miRNAs such as miR-21 and miR-101." (PMID 34206901, 2021). "miR-144 has been identified as a tumor suppressor in CRC, and many studies have reported that EZH2 is the main target gene of miR-144." (PMID 33591945, 2021). "Given the role of EZH2 in early CD4+ T cell differentiation, its targeting should be further investigated as a strategy to modulate CD4+ T cell responses during tumor immunity." (PMID 33859645, 2021). "GBM cells are capable of experiencing molecular subtype transitions under the influence of a diverse tumor milieu resulting in diverse consequences between the in vitro and in vivo experiments by BMI1 and EZH2 inhibitor administration." (PMID 34745848, 2021). "Both pharmacological inhibition and gene knockout of EZH2 in these models led to Treg recruitment of CD8+ and CD4+ effector T-cells, resulting in increased anti-tumour activity." (PMID 34439236, 2021). "It suggested that ARID1A and EZH2 are a pair of important molecules in maintaining the balance of the proliferation and apoptosis of cells while ARID1A serves as the tumor suppressor." (PMID 34715776, 2021). "From these studies, chromatin structure modulators such as Ezh2 and PBAF complex components were revealed to be integral to the tumor cell/T cell interaction." (PMID 33403469, 2021). "Overexpression of EZH2, which is the catalytic unit of PRC2, was reported in MYCN-amplified NB, potentially silencing genes or networks of genes with a tumor suppressive role." (PMID 33404859, 2021). "DOX chemotherapy-elicited CAL51 exosomes were injected around the tumor, and then mice were treated with PBS, DOX, the EZH2 inhibitor tazemetostat or DOX + tazemetostat." (PMID 33823894, 2021). "There are multiple transcriptional factors, such as MYC, EZH2, TRIM24, KLF4, and BRD4, that can regulate AR transcription by binding to its promoter in tumor cells." (PMID 34323404, 2021).
tumor (continued). "PCR assays showed that the MIAT expression levels were downregulated in tumor tissues collected from the sh-MIAT group compared with the controls, and the relative downstream components including EZH2, p16, p15, and p27 decreased significantly." (PMID 34811354, 2021). "It is therefore clinically relevant to assess the protective effects of EZH2 inhibitors on AAA expansion, as well as tumor progression, in cancer patients." (PMID 34571873, 2021). "IHC of EZH2 was performed using a tissue microarray of 79 HGSOC scored (+/−) for lymphovascular invasion (LVI), tumor-infiltrating lymphocytic aggregates ≥1 mm (TIL) and architectural growth patterns." (PMID 34140011, 2021). "The PD-L1 expression in tumor-induced exhausted CD4+ T cells was found to be controlled by the interplay of chromatin remodeling SWI/SNF and PRC2 complexes, suggesting that EZH2 is involved in regulating PD-L1 expression in exhausted CD4+ T cells." (PMID 34737746, 2021). "Recently, curcumin was found to resensitize chemoresistant PC cells to GEM through the inhibition of the enhancer of zeste homolog-2 (EZH2)-lncRNA PVT1-c-Myc axis and inhibit GEM-resistant tumor growth both in vitro and in xenograft mouse models." (PMID 34453639, 2021). "As an explicatory model, preliminary literature data showed that ARID1A alterations increase tumor cell sensitivity to agents targeting the ATR protein, EZH2 or the PI3K pathway." (PMID 33641055, 2021). "The target of miR-26a is Enhancer of Zeste Homolog 2 (EZH2), the catalytic subunit of the Polycomb Repressive Complex that is involved in EMT and is best known to repress a large number of tumor suppressor genes." (PMID 34957087, 2021). "In a preclinical mouse model, the combination of an EZH2 inhibitor (GSK126) and anti-PD1 antibodies suppressed tumor growth of anti-PD-1-resistant HNSCC." (PMID 33800421, 2021). "Collectively, these results confirm that EZH2 is responsible for the impaired expression of miR‐326 and ARRB1 in MBs, which eliminates important checks of tumor growth." (PMID 32920979, 2021). "A possible explanation is that the attenuation of the CD8 T cell function by Ezh2 inhibition is overcome by DNMT inhibitor induced immunostimulatory factors, such as CXCL9 and 10, in the tumor microenvironment." (PMID 33403469, 2021). "In the current study, we identified TCF3 as a direct target of EZH2 and DNMT3B, which acts as a tumor suppressor in EC." (PMID 34175897, 2021). "In patients, higher levels of EZH2 and BMI1 expression correlate with poorer tumor differentiation/higher grade and worse survival." (PMID 34968245, 2021). "qRT-PCR and Western blot revealed that sh-LINC01116 group had inhibited LINC01116 and EZH2 expressions, and increased TPM1 expression in tumor tissues of nude mice." (PMID 33499872, 2021). "Whereas, in a human ovarian cancer model, H3K27me3 induced by EZH2 and DNA methylation catalyzed by DNMT1 at their promoter regions repress the expression of CXCL9 and CXCL10 in tumor cells." (PMID 33868269, 2021). "Once EZH2 is inhibited, PIK3IP1 repression is relieved, leading to apoptotic cell death in tumor cells." (PMID 34213777, 2021). "As to how HAT1 regulates AR expression, there are multiple transcriptional factors, such as MYC, EZH2, TRIM24, KLF4, and BRD4, regulate AR transcription by binding to its promoter in tumor cells." (PMID 34323404, 2021). "Therefore, inhibition of EZH2 function may enhance PD-L1 expression in tumor cells." (PMID 34737746, 2021). "Recent studies showed that EZH2 played critical role in initiation and development of various tumours, and blocking EZH2 signalling by EPZ‐6438 inhibited tumour progression." (PMID 34031939, 2021). "Moreover, EZH2 inhibition substantially increased the intratumoral trafficking of activated CD8+ and CD4+ T cells (decreasing the relative number of regulatory T cells, Tregs) and increased M1 tumor-associated macrophages (TAMs) (decreasing the tumor-promoting M2 macrophages)." (PMID 34830196, 2021).
tumor (continued). "Other factors, such as EZH2, are overexpressed and have a direct positive correlation with AOT histological grade and tumor stage." (PMID 34198989, 2021). "Mechanistically, ARID1A interacts with EZH2 via its C-terminal region and antagonizes EZH2-mediated IFN responsiveness, and the DUF3518 domain of ARID1A is essential for tumor cell IFN-γ response." (PMID 34671561, 2021). "We found that the amplification of EZH2 as well as EED and SUZ12 subunits was not limited to a specific tumor type." (PMID 34202528, 2021). "On the other hand, EZH2 can act as a transcriptional activator of multiple oncogenes in a PRC2-independent manner, promoting tumor progression and therapeutic resistance 16-19." (PMID 34093859, 2021). "The dual inhibition of EZH2 and EHMT2 can induce gene transcription and inhibit tumor cell growth more effectively." (PMID 34409024, 2021). "More importantly, the combinatorial treatment of an EZH2 inhibitor and anti-PD1 significantly suppressed tumor progression of an anti-PD-1 resistant HNSCC model." (PMID 33403469, 2021). "Inhibition of EZH2 and DNMT1 by chemical inhibitors restored the expression of CXCL9 and CXCL10 and increased effector T cell tumor infiltration." (PMID 34262562, 2021). "Given that metformin suppressed expression of EZH2 in SI-NET cells, the effect on SI-NET tumor growth was investigated." (PMID 34815475, 2021). "In our study, we found that most cancer driver genes are specifically expressed in tumor tissue, and we constructed a four-mRNA prognostic signature (ETV5, EZH2, PABPC1, ZCRB1) that has higher predictive power than other clinical features." (PMID 34335239, 2021). "Several EZH2 inhibitors have been specifically synthesized, among which EPZ-6438 (E7438) and 3-deazaneplanocin-A (DZNep) have shown significant anti-tumor activity and have been considered for clinical research." (PMID 34051847, 2021). "Intriguingly, the protein expression of FAK, EZH2, and PCNA significantly inversely correlated with tumor size." (PMID 32806748, 2020). "In the present study, we investigated the molecular mechanisms through which LINC01234 regulated the tumor progression-related behavior of NSCLC cells, and found that LINC01234 interacted with several RNA-binding proteins, including Ago2, EZH2, LSD1 and SUZ12." (PMID 31959200, 2020). "Our study confirmed that miR-33a was a tumor-suppressive miRNA in TNBC and indicated that EZH2 can be a potential therapeutic target for TNBC treatment." (PMID 32206036, 2020). "Hence, the results revealed that the high-risk score may be an essential factor for B and T cell growth and differentiation leading to tumor immunosuppression, and the low expression of EZH2 and AZGP1 and high expression of IGF2BP2 were the main factors of tumor immunosuppression in the risk model." (PMID 33505420, 2020). "NEAT1 can be used as a cofactor to affect the expression of enhancer of zeste homolog 2 (EZH2) and it can also promote tumor invasion and metastasis." (PMID 32612834, 2020). "Enhancer of zeste homolog 2 (EZH2), a member of polycomb repressive complex 2 (PRC2),trimethylates lysine 27 of histone H3 (H3K27me3) and regulates several genesinvolved in tumor development." (PMID 32453339, 2020). "Mechanistically, it has been proposed that EZH2-mediated gene silencing of chemokines, such as CXCL9 and CXCL10, prevents effector T-cell trafficking to the tumor microenvironment, thereby allowing tumor cells to evade immunity." (PMID 33374737, 2020). "Specifically, Carma1, Rel, Nrp1, Ezh2, Senp3, and Ikzf2-null Treg all produce appreciable amounts of IFNγ and/or TNF in the tumor microenvironment." (PMID 33143070, 2020). "Our study revealed a novel mechanism by which miR-3613-3p regulates SMAD2/EZH2 network in TNBC and demonstrated that miR-3613-3p functions as a tumor-suppressive miRNA in TNBC." (PMID 33330073, 2020).
tumor (continued). "The IHC results also confirmed that the positive expression of Ki67 in the tumor tissue decreased after interference with SNHG1, while the positive expression of Ki67 increased after interference with SNHG1 and overexpression of EZH2." (PMID 33194612, 2020). "Subsequently, the researchers designed a highly specific NEK2 inhibitor, CMP3a, which can promote EZH2 ubiquitination degradation and inhibit GBM tumor growth." (PMID 33308321, 2020). "What is more, overexpression of miR-3613-3p substantially inhibited the migration and proliferation of TNBC cells in vitro and tumor proliferation in vivo by targeting SMAD2 and EZH2." (PMID 33330073, 2020). "In tumor cells, EZH2 epigenetically represses negative regulators of mTOR (e.g., TSC2 and RHOA), thus inhibiting tumor cell autophagy and accelerating tumorigenesis." (PMID 32999031, 2020). "Inhibiting Ezh2 expression enhances the activity of anti-CTLA-4 treatment and suppresses tumor growth." (PMID 32867025, 2020). "Treatment with an EZH2 inhibitor can upregulate MHC class I expression, promoting better antigenic presentation by tumor cells and significant tumor suppression when combined with immune checkpoint inhibitors." (PMID 32509576, 2020). "To explore the expression of EZH2 and DLC1 in tumours, we analysed the expression of EZH2 and DLC1 in various tumours based on the secondary online tools of the TCGA database." (PMID 32725802, 2020). "Intriguingly, in our cohort, there was an apparently inverse correlation between tumor size and FAK, EZH2, H3K27me3, and PCNA expression." (PMID 32806748, 2020). "Several EZH2 and allosteric EED inhibitors have been shown to impede tumor growth, both in vivo and in vitro." (PMID 32906688, 2020). "EZH2 can negatively regulate interferon response genes, T helper cell (TH)-1 type chemokines, and major histocompatibility complex (MHC) expression in tumor cells." (PMID 32041674, 2020). "Given the importance of PRC2 as a histone methyltransferase in HCC, we further investigated the interaction between CRNDE and EZH2, SUZ12, and SUV39H1, and found that the inhibitory effect of EZH2, SUZ12, and SUV39H1 on tumor suppressors was mediated by CRNDE." (PMID 32826865, 2020). "EZH2 cooperates with E2F1 to enhance its transcriptional activity and control the mRNA expression of genes involved in the regulation of tumor aggressiveness via direct protein binding." (PMID 33614480, 2020). "Thereafter, we also analyzed the expression patterns of NRON, EZH2 and EMT markers in these tumor samples from nude mice." (PMID 32194786, 2020). "Taken together, our results indicate that miR-9, functioning as a tumor-suppressive miRNA in GBM, is suppressed through epigenetic silencing by EZH2." (PMID 32635336, 2020). "Notably, inhibition of EZH2 upon instilling DZNep treatment could reduce the survival of epithelial OC cells by potentiating the expression pattern of aplysia ras homolog member I, a tumor-suppressor gene." (PMID 33292225, 2020). "EZH2 has also been suggested to promote metastasis through pleiotropic roles in modifying EMT, such as repression of tumor suppressor genes or miRNA, as well as regulation of cancer stem cells and migration." (PMID 33291558, 2020). "When compared to the tumor of control mice, the tumor of PTC596-treated mice with relapse (mice #5 and #6) had lost many the original characteristics, including reduced BMI1, EZH2, and SOX2 expression." (PMID 31934644, 2020). "Our in vitro study confirmed the regulatory mechanism of miR-33a/EZH2 cascade in TNBC progression, thus, more investigation of the effects of miR-33a and EZH2 on tumor growth and metastasis in vivo is needed." (PMID 32206036, 2020).
tumor (continued). "Both DZNep treatment and EZH2 knockdown impeded anchorage-independent sphere formation and cell growth of HCC cells in culture, also pointed that and the tumor-initiating HCC cells are highly dependent on EZH2 for the tumorigenic activity." (PMID 33097694, 2020). "First, lncRNA H19, which is upregulated by forkhead box F2 (FOXF2), can recruit the EZH2 protein to bind to the phosphate and tensin homolog deleted on chromosome ten (PTEN) tumor-suppressor gene." (PMID 33050646, 2020). "IHC showed that the expression of EZH2 was down‐regulated and the expression of DLC1 was up‐regulated in TNBC xenograft tumour tissues treated with curcumin." (PMID 32725802, 2020). "On the other hand, the expression of total and nuclear FAK, EZH2, and PCNA significantly inversely correlated with tumor size." (PMID 32806748, 2020). "After SNHG1 expression was silenced and EZH2 was overexpressed, the protein expression of LC3-II and Beclin-1 in the tumor tissue was significantly reduced while the protein expression of p62 was significantly increased." (PMID 33194612, 2020). "In this study, we identified FOSB as a novel EZH2 downstream target gene in TNBC, and inhibition of which resulted in tumor growth and EZH2is resistance." (PMID 32477007, 2020). "Enhancer of zeste homolog 2 (EZH2), a major histone methyltransferase, plays an essential role in tumor regulation via trimethylating lysine 27 on histone H3." (PMID 31320749, 2020). "In contrast, in the one animal treated with A1016 and that still presented a small tumor of 0.6 mm in diameter, the tumor remained BMI1 and SOX2 positive, although EZH2 levels were reduced." (PMID 31934644, 2020). "It has also been reported that EZH2 expression in TNBC patients is correlated with aggressiveness, advanced tumor stage and increased mortality." (PMID 32206036, 2020). "EZH2 is highly expressed in many kinds of cancers including BC, and EZH2 can regulate TNBC tumor growth and metastasis." (PMID 32206036, 2020). "The same tumor suppressor role was also found for miR-124a, which targets CDK4, CDK6, Cyclin D2, and EZH2 proteins, with its expression being diminished in UM cells." (PMID 33053887, 2020). "For example, the lncRNA ANRIL is able to recruit EZH2 to the promoter region of KLF2, a known tumor suppressor, to induce its epigenetic silencing by trimethylation of the histone H3 at lysine 27 (H3K27me3)." (PMID 32331331, 2020). "Here, we have shown that EZH2 inhibition induced is able to eliminate LMS stem-like cells and to restore the anti-tumor effect of dual PI3K/mTOR inhibition in vitro and in vivo." (PMID 30683135, 2019). "While EZH2 ASO treatment alone only slightly suppressed tumor growth and DTX alone only suppressed tumor growth moderately, co-treatment with EZH2 ASO and DTX resulted in much greater suppression of tumor growth compared to other treatment conditions." (PMID 31410199, 2019). "We further demonstrated that ANLN knockdown significantly inhibited the levels of EZH2 and LASP1 expression in xenograft tumor models." (PMID 31395079, 2019). "Our findings uncover novel and dramatically opposing functions of Ezh2 during AML evolution that are dependent upon the phase of disease, with Ezh2 functioning as a tumor suppressor in AML induction and as a facilitator of disease in established AML." (PMID 30890554, 2019). "Specifically, a positive correlation between urine GOAT levels and the expression levels (in the tumor pieces) of CDK6, EGF, EZH2 and NF-KB was found in patients with PCa." (PMID 31766715, 2019). "NK cell infiltration is capable of driving tumor cell lysis, which is evident by greater TUNEL staining in EZH2 inhibitor-treated HT1376 xenografts." (PMID 30692641, 2019).